IL6 (interleukin 6)
Diseases named in the same sentence as IL6 in open-access papers (continued):
Sharing a sentence is not in itself a finding about the gene and the disease.
COVID-19 (continued). "Our results also highlighted that the interleukin 6 receptor (IL6R) was the target of biochanin A. As a receptor of IL6, it is one of the cytokines induced in patients with COVID-19." (PMID 34931923, 2021). "In patients who develop ARDS and/or MODS later in the clinical course of COVID-19, there is a rationale for pro-inflammatory (notably IL-6) cytokine blockade in order to contain the tissue damage." (PMID 34945111, 2021). "IL-6 biosensors with an effective operating range from 0 to 61.79 pg/mL are crucial to ensure their viability for application in COVID-19 biosensing platforms." (PMID 34205852, 2021). "Both those parameters were correlated (r = 0.424; p < 0.001), and GDF-15 levels also correlated with other biomarkers of COVID-19 severity/mortality, namely, IL-6, CRP, ferritin, D-dimer and neutrophils, and inversely with lymphocyte count." (PMID 34829345, 2021). "Recently, 2 major trials involving the IL-6 antagonists tocilizumab and sarilumab were conducted in COVID-19 patients." (PMID 34496633, 2021). "In critically ill COVID-19 patients, levels of interleukin (IL)-6, which is known to be one of the main pro-inflammatory cytokines in the initiation or amplification of a cytokine storm, have been shown to be significantly elevated." (PMID 34122407, 2021). "Skeletal muscles loss has been linked to pro-inflammatory cytokines such as IL-6 and TNF-α, which are elevated during COVID-19 and correlate with disease severity." (PMID 33668833, 2021). "The high levels of IL-6 observed in COVID-19 patients are apt to elicit Neutrophil Extracellular Traps (NETs) which include extracellular DNA fibers, histones, microbicidal proteins, proteases and oxidant enzymes to be released by neutrophils." (PMID 34912345, 2021). "Several treatment lines suggest that using a monoclonal antibody against IL-6 is an attractive strategy to manage severe COVID-19 as Tocilizumab has the potential to reduce mortality and the need for mechanical ventilation." (PMID 34659270, 2021). "In a subgroup of 49 available plasma samples from COVID-19 patients, collected at a median of 2.8 (2.1–3.7) months after baseline, circulating levels of PAMPs (16S rDNA), DAMPs (mtDNA), and cytokines (IL-6, TNF-α, and IL-10) were quantified." (PMID 34659235, 2021). "Our in vitro study has shown that CVL218 can effectively inhibit the production of several inflammatory cytokines induced by LPS in PBMCs, including IL-6, IL-10, IFN-γ, and TNF-α, which are highly related to the pathogenic characteristics of COVID-19." (PMID 33895786, 2021). "In this classification, Severe cases are characterized by high IL-6 and IL-10 levels, both cytokines previously attributed to increase the immunopathogenesis of COVID-19 and predictive value in Severe cases." (PMID 34262570, 2021). "In conclusion, the results of this multicenter study show for the first time that there is an independent association and an interaction between serum IL-6 levels and MAFLD in hospitalized patients with severe COVID-19." (PMID 33763027, 2021). "Eligible studies were those including laboratory parameters—including serum interleukin-6 levels—from mild, moderate, or severe COVID-19 cases." (PMID 34185801, 2021). "In terms of laboratory parameters, elevated inflammatory cytokines and infection-related factors, such as TNF-α, IL-6, IL-10, IL-8, IL-1β, IL-2R, ferritin, hs-CRP and procalcitonin were significantly associated with higher death risk of COVID-19." (PMID 34521370, 2021). "The IL-6, a novel biomarker for COVID-19 severity, has been correlated with mortality in various studies." (PMID 34616572, 2021). "GDF-15 and IL-6 appeared to be related with disease severity of COVID-19, but their levels were higher in sepsis than in COVID-19 and were associated with prognosis in sepsis." (PMID 35095877, 2021).
COVID-19 (continued). "The excessive IL-6 creates high levels of inflammation that often result in the development of ARDS, which is the leading cause of death from COVID-19 and other coronavirus-related diseases, including SARS and MERS (8, –, 11)." (PMID 34634929, 2021). "For the majority of these cytokines and chemokines, including those that are typically associated with MAS (IL-6, IL-18, IFN-γ, TNF-α, CXCL9) the increase was less pronounced in COVID-19 critical condition than in MAS patients." (PMID 34226537, 2021). "IL-6, as well as its physiological receptors, is therefore considered as a promising therapeutic target in critically ill patients infected by COVID-19." (PMID 37287491, 2021). "Individuals with COVID-19 demonstrate an increase in serum levels of IL-6 within 3 days after disease onset, with even higher levels in severe cases compared to mild ones." (PMID 33584343, 2021). "According to the effects of cytokine storm on liver damage, the inflammation biomarkers such as CRP, serum ferritin, lactate dehydrogenase (LDH), IL-6, IL-2, and D-dimer were significantly higher in severely ill patients of COVID-19." (PMID 34195193, 2021). "Severe COVID-19 patients show increased levels of the granulocyte colony-stimulating factor (G-CSF), IL-2, IL-6, IL-10, monocyte chemo-attractant peptide (MCP)-1), macrophage inflammatory protein 1α (MIP1α) and TNF-α." (PMID 33927728, 2021). "Here, we found the serum levels of IL-6 and IL-8 to have increased with increasing COVID-19 severity with COVID-19 disease progression." (PMID 34335566, 2021). "Patients with CKD were more often treated for COVID-19 with IL-6 inhibitor tocilizumab (TCZ), dexamethasone, and low molecular weight heparin compared with patients without kidney abnormalities." (PMID 34068725, 2021). "Similar to NF-κB TFs, AP-1 TFs (FOS and JUN) are critical regulators of inflammatory cytokine genes such as CCL2 and IL6, which are expressed at high levels in COVID-19 patients." (PMID 34163359, 2021). "Regarding this, it is well known that the pro-inflammatory cytokine IL-6 plays an important role in the pathogenesis of the cytokine storm, and studies have revealed a correlation between high levels of IL-6 and severe status of COVID-19." (PMID 33596401, 2021). "Regarding other modalities in the management of severe COVID-19 patients, tocilizumab (IL-6 antagonist) has been used to overcome the cytokine storm and development of ALI and ARDS." (PMID 33967777, 2021). "In our study, the levels of seven cytokines in COVID-19 patients (IL-6, IP-10, IL-8, MIG, MIP-1β, IL-18, TNF-α) were different from those in healthy controls, while M-CSF, MCP-1, FLT-3, VEGF, IL-1RA, EGF, eotaxin and MCP-1 were not different." (PMID 34539644, 2021). "It is worth noting that some meta-analyses have confirmed the influence of cytokines elevation, mainly IL-6, in severe COVID-19." (PMID 34440767, 2021). "Other immune-inflammatory biomarkers, such as higher levels of interleukin-6 (IL-6), C-reaction protein (CRP) and Procalcitonin (PCT) were independent risk factors for assessing the severity of COVID-19 in patients." (PMID 34488665, 2021). "In summary, amygdalin is a candidate compound for COVID-19 treatment by regulating IL6, SRC, MAPK1, EGFR and VEGFA by way of the PI3K-Akt signalling pathway, VEGF signalling pathway and MAPK signalling pathway." (PMID 34908920, 2021). "-The main cytokines involved in severe COVID-19 cases (IL-6 and TNF-α) are downstream of the TLR4 signaling pathway." (PMID 33981312, 2021). "Proinflammatory cytokines, particularly IL-6 through the activation of the Jak-Stat pathway, have been identified as a prognostic indicator for mortality among COVID-19 patients." (PMID 34220430, 2021). "IL-6 is one of the key pro-inflammatory cytokines found in COVID-19 patients, which is why anti-IL-6/IL-6R biological drugs have been used for the treatment of this disease from the beginning." (PMID 34073559, 2021).
COVID-19 (continued). "A recent study has revealed that IL-6 above 37.65 pg/ml is a significant predictor of mortality in COVID-19 patients." (PMID 33988463, 2021). "Among the elevated cytokines that are discovered in severe COVID-19 patients, the blood level of IL-6 was particularly elevated." (PMID 34698139, 2021). "In line with recently published research, we found an age dependent increase of IL-6 and IL-8 in our COVID-19 cohort." (PMID 34943881, 2021). "Persistent elevation of serum IL-6 levels is an indicator of poor prognosis and can possibly lead to death in COVID-19 patients." (PMID 33988463, 2021). "Our data demonstrated that after being induced by Prot_S, Calu-3 cells showed the upregulation of TNFα, IL6, IL1β, and IFNγ, which is in line with the clinical situation of patients with COVID-19." (PMID 34074129, 2021). "The critical role of the Th17 subset of CD4+ T cells, possibly IL-6-induced, in COVID-19 immunopathology and vaccine-induced immune enhancement was highlighted by recent studies." (PMID 35004790, 2021). "It has been found that proinflammatory cytokines such as TNF-α, IL-6, IL-10, IL-1β and chemokines increase in COVID-19 patients." (PMID 34284532, 2021). "Co-staining with CD163 revealed that proinflammatory cytokines IL-1β, IL-6, and IL-18 were more highly expressed in the pulmonary macrophages of COVID-19 patients than in those of control donors." (PMID 34960782, 2021). "In patients with severe COVID-19, high levels of circulating IL-6, IL-1β, INFγ, and TNF-α have been reported, together with an unbalanced white cell formula, consisting of high neutrophils and decreased CD4+ and CD8+ T cells." (PMID 35140702, 2021). "Severe COVID-19 patients tend to show elevated circulating amounts of the proinflammatory mediators Interleukin-6 (IL-6), IL-8, IL-1β, and Monocyte Chemoattractant Protein-1 (MCP-1)." (PMID 33968948, 2021). "Comparing these profiles to archived samples from patients with fatal influenza, IL-6 was equally elevated in both conditions whereas GM-CSF was prominent only in COVID-19." (PMID 33692097, 2021). "Several Th1 cytokines such as IFN-γ, IL-1, IL-6 and IL-12 were observed to be grossly elevated in COVID-19 patients and continue to remain elevated for at least 2 weeks after the disease." (PMID 33988463, 2021). "Disruption of the integrity of tight junctions in between enterocytes of the gut called “leaky gut” in COVID-19 patients is responsible for the development of diarrhea, and inflammation due to higher levels of IL-6 in plasma and fecal calprotectin." (PMID 33791231, 2021). "The SARS-CoV-2 induced COVID-19 evoked overexpression of pro-inflammatory cytokines such as IL-6 and TNF-α, which are products of the TLR-4 pathway." (PMID 34200327, 2021). "The cytokine profiling of COVID-19 patients in our study provided further evidence that the CRS-associated cytokines, such as IL-6, IL-1β, IL-10, IL-18, and IFN-γ, were dramatically elevated in severe patients." (PMID 33712622, 2021). "Tocilizumab, a recombinant anti-human IL-6 receptor (IL-6R) monoclonal antibody, can block IL-6 signaling transduction and its mediated inflammatory response 7, 8, and thus has attracted much attention on its therapeutic effects in COVID-19 patients." (PMID 34131411, 2021). "It is widely recognized that IL-6, an important biomarker of inflammation for multiple conditions, has a crucial role in COVID-19 cytokine storm." (PMID 34675240, 2021). "The analysis of basal cytokine profile revealed that COVID-19 patients had higher levels of IL-10 (15.2 (12.5) vs. 1.2 (1.4) pg/mL, p = 0.02), while the levels of IL-6, IL-8 and sTLR4 were comparable." (PMID 33808205, 2021). "In a SARS-CoV-2 infection, a pro-inflammatory cytokine storm is a primary event characterized by increases in IL-1β, IL-6, and TNF-α, and even moderately elevated IL-6 levels have been associated with a high risk of respiratory failure in COVID-19 patients." (PMID 34572292, 2021).
COVID-19 (continued). "Patients with suspected myocarditis were older, had a higher frequency of previous cardiac disease, and significantly more prolonged hospitalization and a lower value of interleukin-6 than other COVID-19 patients." (PMID 33663062, 2021). "Elevated levels of pro-inflammatory cytokines including tumor necrosis factor alpha (TNF-α), interleukin (IL)-1 and IL-6, as well as lymphopenia, are the most prevalent cytokine profile shifts in COVID-19 patients with severe or terminal disease." (PMID 34205044, 2021). "Elevated levels of IL-6 among other factors of innate immune hyperactivation are considered responsible for a more severe course of disease of COVID-19 patients." (PMID 33527083, 2021). "Two meta-analyses of IL-6 and IL-10 circulating levels found a correlation between the disease severity and mortality in COVID-19 patients." (PMID 34646263, 2021). "Systemic levels of IL-6 are elevated in COVID-19, and a small prospective observational study revealed that a higher level of IL-6 was associated with an increased risk of developing PD." (PMID 34942956, 2021). "Among them, IL-6 was found to play the most important role in “cytokine storm” in COVID-19 patients." (PMID 34602072, 2021). "Levels of IL-6 correlated with COVID-19 severity and IL-6 has a key role in cytokine storm and the inflammatory cascade." (PMID 34067072, 2021). "IL-6 levels in severe COVID-19 patients were significantly increased above those in moderate COVID-19 patients, comorbidity control patients, and healthy donors." (PMID 33986193, 2021). "According to China’s National Health Commission, tocilizumab should be investigated for the treatment of COVID-19 infected people who have high IL-6 levels and substantial lung damage." (PMID 34835248, 2021). "In non-COVID-19 patients, inflammatory biomarkers, such as IL-6 and sTNFR-1, were moderate to highly correlated with Ang-2 and Ang-2:1 ratio (range of correlation 0.53–0.71)." (PMID 33874973, 2021). "In COVID-19 patients with acute respiratory distress syndrome (ARDS), fibrinogen levels were reported to be associated with elevated interleukin-6 values." (PMID 34414135, 2021). "The analysis of IL6 as the core target of LHQW in treating COVID-19 showed that there were five biological processes that included IL6 in the top five biological processes in which the junction targets were involved (P ≤ 0.05)." (PMID 34731090, 2021). "A high release of cytokine in response to viral infection is documented in COVID-19 patients with adverse clinical outcomes and IL-6 is a key element of the cytokine storm syndrome leading to multi-organ damage." (PMID 33216184, 2021). "High levels of IL-6 is widely described in relation to COVID-19, and its level corresponds to the severity of the disease." (PMID 34575258, 2021). "Spike protein induced the generation of IL-6 in cultured cells as well as in COVID-19 positive patient sera, and AT1 receptor antagonist (candesartan cilexetil) resulted in downregulation of MAPK activation as well as IL-6 release." (PMID 33854432, 2021). "A recent randomized controlled trial study demonstrated that administration of curcumin in nano micelles form significantly decreases IL6 and IL-1β in COVID-19 patients." (PMID 34513735, 2021). "There is reported to be a higher level of IL-10 in COVID-19 patients compared to healthy controls, which is correlated with IL-6 concentrations and disease severity." (PMID 35126355, 2021). "COVID-19 patients had a lower number of natural killer (NK) cells in peripheral blood, and high levels of IL-6 correlated with a lower number of NK cells." (PMID 34578460, 2021). "Concomitantly, the levels of cytokines such as IL-4, IL-6, and IL-10 are also increased in the sera of patients with COVID-19 compared with those of controls." (PMID 34360684, 2021). "Interleukin-6 (IL-6) as well as white blood cell count were significantly higher in the control cohort than in the COVID-19 cohort (each p < 0.05)." (PMID 34110585, 2021).
COVID-19 (continued). "Based on findings from previous studies and our report, we suggest that ACEi or ARBs function by controlling RAAS and the modulation of the levels of cytokines, such as IL-6 in patients with COVID-19." (PMID 34285712, 2021). "MCs produce IL-6 in response to viruses and serum IL-6 has been shown to be a valuable biomarker of COVID-19." (PMID 34359931, 2021). "It was recently shown that the total number of CD4+ T cells, CD8+ T cells, B cells, and NK cells in patients was markedly decreased in the most severe forms of COVID-19 and that there is an increase of IL-2, IL-6, IL-10, and IFN-γ." (PMID 34552938, 2021). "We noticed that our PD COVID-19 patients had statistically significant higher peak WBC counts and higher base creatinine kinase, ferritin, LDH, lactate, ALT, AST, and IL-6 levels compared to HD COVID-19 patients." (PMID 34293004, 2021). "One study identified a correlation between serum sodium and interleukin-6 and greater correction of hyponatraemia in patients with COVID-19 who were treated with tocilizumab." (PMID 34292875, 2021). "This analysis shows that plasma levels of HA and hyaluronidase in patients with COVID-19 each are correlated with inflammatory cytokines known to have roles in either HA synthesis or degradation such as IL-6, IL-8, MCP-1, TNF-α, and IP10." (PMID 34314391, 2021). "We investigated changes in angiotensin II and IL-6 levels in four COVID-19 patients treated with ARBs." (PMID 34285712, 2021). "Compared with gp96, IL-6 alone showed slightly weaker prediction of severe COVID-19 with an AUC of 0.792 (95% CI, 0.605 to 0.917; P < 0.05)." (PMID 34817280, 2021). "Data regarding interleukin-6 (IL-6) in MIS-C is poor, but there is a growing interest in IL-6 inhibitors given the improved outcomes in COVID-19 adults treated with tocilizumab." (PMID 34869111, 2021). "Currently, five RCTs are ongoing to ascertain the therapeutic potential of anti-IL-6 antibody in COVID-19 (NCT04381052, NCT04348500, NCT04494724, NCT04343989, NCT04343989)." (PMID 33465050, 2021). "These patients had high IL-1β, IL-6 and IL-8 protein levels in BALF, a finding that was reproduced in a study entailing four patients with COVID-19 associated ARDS." (PMID 34054832, 2021). "Elevated concentration of IL-6 had been indicated as a stable indicator for the progression and adverse endpoint of COVID-19, and IL-6 and IL-10 were significantly related with the positivity duration of SARS-CoV-2, which were consistent with our findings." (PMID 33542929, 2021). "The mAbs selected to treat COVID-19 patients with high IL-6 levels include tocilizumab, sarilumab, and siltuximab." (PMID 34073559, 2021). "Given that IL-6 was also reported to be aberrantly hyperactivated in many types of cancer, in this section, we will discuss the interplay of COVID-19 and cancer in IL-6/Janus kinase (JAK)/signal transducer and activator of transcription (STAT) signaling." (PMID 34001144, 2021). "The plasma IL-6 levels of the patients with COVID-19 on day 1 and the sepsis patients on days 1 and 2-3, and the plasma amphiregulin levels of the sepsis patients on day 1, were significantly higher than those of the healthy controls." (PMID 35095877, 2021). "Among biomediators involved in severe and critical cases of COVID-19, interleukin (IL)-6 is highly elevated and can be used a prognostic marker." (PMID 34631752, 2021). "IL-6 is elevated in COVID-19 patients with severe disease and it is also considered a relevant prognostic marker." (PMID 33658032, 2021). "The clinical interpretation of their important roles was that patients with severe COVID-19 experience more intense immune responses and hyperinflammation, such as cytokine storm syndrome, with substantially increased IL-6." (PMID 33714935, 2021).